IL6 (interleukin 6)
Diseases named in the same sentence as IL6 in open-access papers (continued):
Sharing a sentence is not in itself a finding about the gene and the disease.
COVID-19 (continued). "The high rates of cardiovascular disease, pulmonary disease, older age, elevated IL-6 and D-dimer levels that we observed in our cohorts are common features in COVID-19 patients, and are potential predictors of mortality within the wider NYC cohort and elsewhere." (PMID 35794523, 2022). "In COVID-19, activation of TLRs lead to activation of inflammasome, production of IL1β and IL-6." (PMID 36202985, 2022). "Accordingly, we evaluated the levels of IL-17, IFN-γ, TNF-α, IL-10, IL-6, IL-4 and IL-2 in patients with clinical COVID-19 and long COVID-19, with cases classified as mild, moderate and severe, and associations with risk factors for sex, age and presence of comorbidities." (PMID 35846757, 2022). "During the first wave, which occurred between March and May 2020, we studied 35 COVID-19 patients at hospital admission demonstrating that serum IL-6 was increased in all cases with a significant relationship with disease severity." (PMID 35893398, 2022). "Besides IL-6, patients with severe cases of COVID-19 have higher plasma levels of other elements of cytokine storms, including IL-2, IL-7, IL-8, IL-10, and tumor necrosis factor-α (TNF-α)." (PMID 35295802, 2022). "In COVID-19 pathogenesis, the prothrombotic state is due to the effects of IL-1 and IL-6." (PMID 36289881, 2022). "Notably, except for effector memory T4 cells, plasma blasts and Tregs, the number of all lymphocyte subsets was markedly decreased in COVID-19 patients with IL-6 levels over 30-fold higher than those in healthy cases." (PMID 36403042, 2022). "This cell-host interaction is important as many of the cytokines produced in response to COVID-19 (i.e., interleukin-1 beta (IL-1β), IL-2, IL-6, IL-8, IL-10, and tumor necrosis factor alpha (TNFα)) stimulate infiltration of macrophages, monocytes, and neutrophils into the lung tissue." (PMID 35033181, 2022). "While most randomized trials in COVID-19 have focused in modulating the IL-1/IL-6 pathway, data from multiple studies suggest that anti-TNF treatments may also play a role in the therapeutic armamentarium." (PMID 36405747, 2022). "Indeed, a synergy between NF-κB and STAT3 molecules based on pro-inflammatory cytokines (i.e., IL-6), which act as inflammation amplifier, was reported in several multiple inflammatory and autoimmune diseases and postulated also in COVID-19." (PMID 34518653, 2022). "First, IL6 itself can be considered a valuable therapeutic target in treating COVID-19 patients." (PMID 36195636, 2022). "Moreover, an anti-IL-6 monoclonal antibody decreased IL-6 levels, which lead to the reduction of the inflammatory process in COVID-19 patients with severe respiratory disease." (PMID 36341384, 2022). "IL-6 is a proinflammatory factor released in severely ill COVID-19 patients." (PMID 36175845, 2022). "Consequently, anti-Il-6 medications were proposed for the treatment of severe COVID-19, and tocilizumab (TOC) is the one most often used." (PMID 35887600, 2022). "However, a transcriptional study performed on lung tissue has shown that the expression of IL-6 was not affected by SARS-CoV-2 infection, raising a question about the role of IL-6 therapies in COVID-19." (PMID 36422642, 2022). "As a result, each interleukin-6, lymphocytes, and neutrophils may be considered as major factors that affect the severity of COVID-19 through an inverse correlation." (PMID 35721343, 2022). "Moreover, the levels of CXCL10 and IL-6 are more than 10 times higher in patients with severe course and mild–moderate COVID-19 in comparison to healthy volunteers." (PMID 35409036, 2022). "Therefore, modulating the levels of IL-6 or its effects is a highly critical point and therapeutic target for COVID-19 patients." (PMID 35385549, 2022). "Interestingly, IL-6 levels have recently been used to predict severity and survivability in COVID-19 patients as part of a cytokine signature, demonstrating the importance of IL-6 as a key early mediator of the inflammatory cascade." (PMID 35277071, 2022).
COVID-19 (continued). "The S1 spike protein stimulated the production of cytokines: in human lung A549+ cells, we found that S1 spike stimulated the production of the key COVID-19 cytokine IL-1β, and in human intestinal epithelial Caco-2 cells, S1 stimulated the production of IL-6 and IL-8 cytokines." (PMID 36296272, 2022). "In the case of IL-6, patients from Lima had a mean level of 16.2 pg/ml (healthy) and 48.3 pg/ml (COVID-19), meanwhile, patients from Huaraz had levels of 67.3 pg/ml (healthy) and 97.9 pg/ml (COVID-19)." (PMID 35090394, 2022). "In addition, serum levels of IL-6 were higher in patients who died of COVID-19 than in those who recovered." (PMID 36363785, 2022). "Moreover, IFN-γ, IL-1Ra were predictors of remarkable radiological findings, whereas high IL-6 and granzyme B were found to predict liver injury in COVID-19 patients." (PMID 35529862, 2022). "Giuseppe M. SARS-CoV-2 and COVID-19: Is interleukin-6 (IL-6) the ‘culprit lesion’ of ARDS onset?" (PMID 35804458, 2022). "The COVID-19 responsive inflammatory molecules, such as IL-6 and IL-8 and tumor necrosis factor-α may be beyond these changes." (PMID 35350852, 2022). "First, tryptophan supplementation or improvement of the tryptophan metabolic pathway may prevent severe COVID-19; second, blockade of IL-6 and IL-1β may prevent severe COVID-19 by protecting against circulatory disturbance caused by thrombosis." (PMID 36035409, 2022). "When IL-6 binds to the membrane IL-6 receptor, it activates the JAK-STAT and PI3K-AKT signaling pathways, and thus plays a key role in causing cytokine storm in COVID-19 patients." (PMID 36081604, 2022). "IL-6, produced by various immune cell types and a well-known mediator of the proinflammatory response, and MCP-1, involved in the infiltration and migration of monocytes, have previously been associated with COVID-19 patients and the disease severity." (PMID 35831294, 2022). "Higher PE levels as represented by the LRS and even a single PE derived from the LRS could prognosticate for severe critical illness with combined with ISS and IL-6 in trauma or when used alone in COVID-19." (PMID 36357394, 2022). "Herein, we discovered that age (≥60 years V < 60 years), dyspnea (yes V no), lymphocyte count (low V normal), CRP (high V normal) and IL-6 (high V normal) were independent factors to infer the severe disease occurrence out of common type of COVID-19, in which age was the most important contributor." (PMID 35037900, 2022). "IL-6 levels showed a slight correlation with advanced age in acute COVID-19." (PMID 35846757, 2022). "The expressions of PAI-1 and IL-6 in severe COVID-19 patients." (PMID 35784318, 2022). "The model suggested LDL-C (p < 0.001), HDL (p < 0.001), TC (p < 0.001), TG (p < 0.001), free T3 (p < 0.001), free T4 (p < 0.001), TSH (p < 0.001), IL-6 (p < 0.001), Procalcitonin (p < 0.001), CRP (p < 0.001), and D-dimers (p = 0.021) as independent risk factors for COVID-19." (PMID 35637852, 2022). "Some biomarkers to monitor disease state assess severity of COVID-19 patients have been identified including IL-6, C-reactive protein (CRP), alanine aminotransferase (ALT), aspartate aminotransferase (AST), plasma D-dimers as well as leukocyte and lymphocyte counts." (PMID 35064792, 2022). "In summary, our preliminary results suggest that nimotuzumab is a safe antibody that might reduce IL-6 and PAI-1 and prevent fibrosis in severe and moderate COVID-19 patients at high risk of aggravation." (PMID 35306855, 2022). "This could be attributed to the cytokine storm; elevation of the inflammatory mediators as erythrocyte sedimentation rate (ESR), interleukin (IL)-6, and C-reactive protein (CRP), which may cause severe disease with worse outcomes in COVID-19 patients." (PMID 36154838, 2022). "For example, IL-6 has been shown as an important marker of COVID-19 severity." (PMID 36389824, 2022). "Indeed, several studies have reported some efficacy in combating COVID-19 by blocking IL-6 activity." (PMID 35392091, 2022).
COVID-19 (continued). "Moreover, SARS-CoV-2 triggered inflammatory response with upregulation of IL-6, which is elevated in COVID-19 patients and correlates with adverse clinical outcome." (PMID 35332140, 2022). "While recruitment was ongoing for the COV-AID trial and the EU-SolidAct trial, patients received compassionate use of IL-6 blockers and of tofacitinib, respectively, despite a lack of evidence showing the clear efficacy of either drug in hospitalized patients with COVID-19." (PMID 35891407, 2022). "In this respect, IL-6 has a dual role as it promotes germinal centre formation and virus clearance but also promotes systemic inflammation in the early viral and late inflammatory phases of COVID-19, respectively." (PMID 36430430, 2022). "Based on these results, the impediment of ROS/Ca2+/IL-6 pathway may be another explanation for the beneficial role of metformin in COVID-19." (PMID 36484892, 2022). "In COVID-19, a cytokine storm occurs and IL-6 increases during the inflammatory phase of COVID-19." (PMID 36107550, 2022). "IL-6 is one of the main cytokines involved in the COVID-19 inflammatory storm." (PMID 35050236, 2022). "However, the elevated concentration of IL-6 and IL-10 persisted also in recovered post-COVID-19 sera." (PMID 36585712, 2022). "Multiple studies suggest that excessive inflammatory production of proinflammatory cytokines such as IL-6 and TNF-α may trigger ARDS, which will accelerate disease progression and increase the risk of death in COVID-19 patients." (PMID 35450063, 2022). "The EAT inflammatory secretome, such as interleukin-6 (IL-6), cytokine found in excess in severe COVID-19 patients, may be a key element in cardiac complications." (PMID 35326442, 2022). "Expect for unbalanced cell compartments, the state of immunosuppression was accompanied by a pathological state of hyper-inflammation, which was marked by elevated levels of cytokines, such as IL-6 and IL-8, also occurs in COVID-19, especially in moderate and severe disease." (PMID 36069182, 2022). "Similarly, Chen and co-authors reported the correlation between high concentrations of plasma IL-6 and TNFα and the severe course of COVID-19." (PMID 35213582, 2022). "In severe COVID-19 cases, the production of pro-inflammatory cytokines, including IL-1β, IL-6 and TNF-α, is increased leading to the generation of cytokine storm, inducing futher unfovarable outcome and may eventually lead to lymphopenia." (PMID 35911748, 2022). "Elevated serum level of IL-6 is the indication for TCZ therapy in COVID-19 patients." (PMID 35308307, 2022). "Also, few other studies have demonstrated a higher number of COVID-19-related deaths, particularly in patients with high IL-6 cytokine levels." (PMID 35573503, 2022). "Once activated, NLRP3 inflammasome causes the release of several proinflammatory cytokines, including IL-6 and IL-1β, which have been reported to have a key role in the pathogenesis of acute lung injury, included COVID-19, affecting type II alveolar epithelial cells ACE2 expression." (PMID 35336077, 2022). "IL-6, through induction of proinflammatory chemokines and cytokines, plays a critical role in the progression from mild inflammation to hyperinflammatory conditions, CRS, ARDS and corresponding lung damage causing mortality in critically ill COVID-19 patients." (PMID 36012968, 2022). "This asserts the vicious cycle of PAI-1 and IL-6 in COVID-19." (PMID 35784318, 2022). "In addition, B cells from acute COVID-19 patients showed increased IL-6 and decreased IL-10 production compared with healthy B cells." (PMID 36357845, 2022). "In this review article, we highlighted the functions of IL-6 in the coronavirus, especially in COVID-19, showing that IL-6 activation plays an important function in the progression of coronavirus and is a rational therapeutic goal for inflammation aimed at coronavirus." (PMID 36506506, 2022).
COVID-19 (continued). "The role of inflammation in driving COVID-19 morbidity and mortality has also been studied in clinical trials using anti-inflammatory therapies, including glucocorticoids and IL-6 inhibitors, and reporting their improving effects on mortality and organ complications in severe COVID-19 patients." (PMID 35053424, 2022). "An increase in TF expression could be seen in patients with COVID-19 due to damage and inflammation of the lung tissue that leads to the increase in IL-6 levels." (PMID 36010203, 2022). "In addition to IFNs, a number of pro-inflammatory cytokines, including members of the IL-1 family, IL-6, IL-8, and TNF have been implicated in COVID-19 pathogenesis and linked to severe disease." (PMID 36189236, 2022). "Moreover, higher expressions of epithelial cell-derived IL-6 and myeloid-derived IL-1β in lung tissues are distinguishing features of COVID-19 compared with healthy controls, influenza pneumonia, bacterial pneumonia, and acute respiratory distress syndrome." (PMID 35248063, 2022). "In some patients extremely high serum IL-6 levels were noted, suggesting severe systemic inflammation, and IL-6 remained persistently positive over time in > 95% of more than 700 samples taken over a median period of around 1 month during COVID-19-related hospitalization." (PMID 35057809, 2022). "A significant amount of the cytokine IL-6 is produced by macrophages during COVID-19, suggesting they may contribute to excessive inflammation." (PMID 35955740, 2022). "The admission level of IL-6 is considered as a predictor to determine whether patients with COVID-19 need mechanical ventilation." (PMID 35295802, 2022). "Moreover, IL-6 plays a crucial role in the pathology of COVID-19 as it modulates the chemotaxis of neutrophils and lymphocyte exhaustion and necrosis." (PMID 35464491, 2022). "In patients hospitalized with COVID-19, Ang-2, IL6, and MPO were associated with mortality, but without conclusive evidence of specificity for COVID-19." (PMID 36403043, 2022). "Patients with severe COVID-19, similar to SARS and MERS patients, have been proposed to have a CRS defined by an elevation in IL-6, which indicates that it may aggravate lung damage, cause viral inflammatory response and death." (PMID 36506506, 2022). "This cytokine storm in COVID-19 is characterized by elevated levels of IL-6 and TNF- expression." (PMID 36431122, 2022). "Moreover, high serum levels of cytokines, such as IL-6, CCL2, CXCL8, CXCL10, IL-2, and IL-10 were associated with COVID-19-related encephalopathy and showed an enhanced systemic inflammatory response." (PMID 36232655, 2022). "A study showed that blockade of IL-6 can reduce COVID-19-induced CRS." (PMID 35168674, 2022). "In both iMCD and COVID-19, increasing the local mAb concentration from 10% to 100% increased inhibition of IL-6 bioactivity, with a sustained full blockade of IL-6 bioactivity with combination treatment, even in the scenario of severe COVID-19 with a cytokine storm." (PMID 35928820, 2022). "Patients with severe COVID-19 had a greater IL-6/IFN ratio than those with mild COVID-19, which might be due to a stronger cytokine storm promoting lung injury." (PMID 36506506, 2022). "The implication of TNFRs and IL-6 in COVID-19 severity appears to be slightly different." (PMID 36219652, 2022). "In addition, no significant change in the transcription levels of IL-6 in PBMC of COVID-19 patients was detected, indicating that the source of IL-6 in the serum is mainly the lung epithelial cells." (PMID 35062368, 2022). "In addition, several biomarkers of frailty and aging have also been found to be related to COVID-19 progress, including elevated C-reactive protein, interleukin-6, lactate dehydrogenase, cortisol, and low vitamin D levels." (PMID 36244048, 2022).
COVID-19 (continued). "While the treatment of COVID-19 with immunosuppressive medications such as glucocorticoids or immunomodulatory medications such as IL-6 antagonists is supported by current data for specific clinical scenarios; these data are not necessarily generalizable to persons with concomitant active TB." (PMID 36233523, 2022). "Moreover, IL-6 level in saliva of COVID-19 patients was positively correlated with serum ferritin (P < 0.0001), and had a positive trend with D-dimer and CRP." (PMID 36163397, 2022). "It is notable that in our study, easily accessible biomarkers (i.e., ferritin, fibrinogen) showed comparative performance with IL-6 and some of the blood-based biomarkers tested for post-acute COVID-19, while for 30-day mortality, outperformed Il-6 (i.e., NLR, MLR, hs-CRP)." (PMID 35741183, 2022). "A striking phenotype perturbation of Tregs showing the over-expression of pro-inflammatory cytokines, such as Treg COVID-19 phenotype-inducers, interleukin (IL)-6 and IL-18 were found in severe COVID-19 cases compared with mild cases, recovered patients, and healthy donors." (PMID 36069182, 2022). "NETs and IL-6 have been studied extensively in pulmonary infections including COVID-19, and the findings are more consistent with the results of our study in concluding that circulating NETs and IL-6 could suggest respiratory infections." (PMID 36199667, 2022). "However, the opposite effect, namely decreased levels of IL-4, IL-6, IL-8, IL-10 and IL-17, were observed in convalescent patients after moderate/severe COVID-19, compared to mild convalescents and healthy controls." (PMID 35757700, 2022). "Additionally, the levels of IL-6 were observed to be significantly elevated in the COVID-19 patient group compared with the control group." (PMID 36558489, 2022). "In COVID-19, the release of pro-inflammatory mediators in the cytokine storm, primarily interleukin-6 (IL-6), has been hypothesized to induce pulmonary intravascular coagulation." (PMID 37841828, 2022). "While several studies have shown that elevated concentrations of IL-8 and TNFα correlate with severity of COVID-19, IL-6 dysregulations appear to have the most profound effect in CS, with high concentrations associated with respiratory failure, poor prognosis and mortality." (PMID 35500008, 2022). "Tocilizumab, a monoclonal IL-6 antibody, and Janus kinase inhibitors such as baricitinib can be considered in the treatment of patients with moderate disease severity according to the German national guideline for the therapy of COVID-19." (PMID 36056419, 2022). "These profile differences may also explain why TNFR is a better predictor of mortality than IL-6 in COVID-19 patients." (PMID 36219652, 2022). "The main pathophysiological culprit of the cytokine storm in COVID-19 is IL-6." (PMID 36295550, 2022). "Although insulin has been shown to exhibit anti-inflammatory action, it remains to be seen whether this is true for COVID-19 patients or contrary to that IL-6 increases insulin resistance, and hence its anti-inflammatory effects are overcome." (PMID 35530861, 2022). "Therefore, in the COVID-19 inflammatory environment, it is possible to imagine that AhR engagement is achieved by Kyn activation and/or by a possible IL-6-dependent STAT-3 modulation of AhR gene expression." (PMID 35203299, 2022). "Thus, this significantly higher proportion of Roma patients with severe COVID-19 that showed high levels of IL-6 at admission can explain why these patients also had continuously elevated inflammatory markers at admission, such as CRP and ESR." (PMID 36431254, 2022). "Background and Objectives: Mortality and illness due to COVID-19 have been linked to a condition known as cytokine release syndrome (CRS) that is characterized by excessive production of inflammatory cytokines, particularly interleukin-6 (IL-6)." (PMID 36676678, 2022). "Furthermore, TNF induced the production of IL-6 and other cytokines, involved in the process of CS in COVID-19." (PMID 35350754, 2022).